CRP (C-reactive protein)
Diseases named in the same sentence as CRP in open-access papers (continued):
Sharing a sentence is not in itself a finding about the gene and the disease.
Insulin resistance (continued). "CRP is also produced in adipocytes and can be overexpressed in individuals with central obesity, ultimately leading to insulin resistance and diabetes." (PMID 38248733, 2023). "IL-1, TNF-α, C-reactive protein (CRP), and monocyte chemoattractant protein-1 (MCP-1) are associated with skeletal muscle insulin resistance." (PMID 37876013, 2023). "CRP in pregnancy and in the early postpartum predicted higher insulin resistance: both higher hepatic insulin resistance (HOMA-IR) and lower whole body insulin sensitivity (MATSUDA) at 1-year postpartum." (PMID 37891561, 2023). "IL-6 increases the production of acute-phase reactants such as C-reactive protein (CRP) and contributes to increased insulin resistance." (PMID 37112628, 2023). "It is associated with elevated inflammatory markers, such as C-reactive protein, interleukin 6 (IL-6) and tumor necrosis factor (TNF), which can increase insulin resistance." (PMID 36810280, 2023). "Higher levels of triglycerides, apolipoprotein B, homeostasis model assessment of insulin resistance, ultrasensitive C-reactive protein, serum amyloid A, and carotid intima-media thickness were observed in the overweight group." (PMID 37341220, 2023). "Insulin resistance was positively correlated with old age, male sex, low educational level, low income, current smoking, high hs-CRP levels, and the presence of at least one chronic disease." (PMID 38041195, 2023). "CRP in the early postpartum predicted higher insulin resistance (higher HOMA-IR, lower MATSUDA) and absolute insulin secretion (HOMA-B and AUCins/glu) but reduced relative insulin secretion (ISSI-2) at 1 year postpartum (p ≤ 0.010)." (PMID 37891561, 2023). "Multiple linear regressions were used to investigate the association of FDII with Homeostatic Model Assessment for Insulin Resistance (HOMA-IR), hs-CRP, Triglyceride Glucose Index (TyG), and Lipid Accumulation Product Index (LAP)." (PMID 36627587, 2023). "When stratified, 25 miRNAs correlated with PCBs in controls compared to only one (hsa-miR-193a-5p) in PCOS; none of these miRNAs correlated with the metabolic parameters of BMI, insulin resistance, or inflammation (C-reactive protein, CRP)." (PMID 37790603, 2023). "CRP during pregnancy correlated with increased weight and body fat, as well as insulin resistance (HOMA-IR) and absolute secretion (HOMA-B), partly independent of weight." (PMID 37891561, 2023). "CRP concentrations are elevated in women with PCOS and has been closely linked to the insulin resistance." (PMID 37660067, 2023). "The positive correlation between CRP concentrations and HOMA-IR suggests that insulin resistance is linked to low-grade chronic inflammation." (PMID 37660067, 2023). "They reported that NLR, LDL, total cholesterol, CRP, systolic and diastolic blood pressures, and presence of insulin resistance was significantly higher in patients with rosacea than in controls." (PMID 37277425, 2023). "The most vital associations have been discovered between levels of C-reactive protein (CRP), central adiposity, and insulin resistance." (PMID 38248733, 2023). "We have also examined the potential association between changes in insulin resistance and fasting and postprandial PYY and GLP1 hormones, adiponectin, RBP4, FGF21 and CRP over 3 years of follow-up." (PMID 37055514, 2023). "The median (IQR) expression level of miR-122 was higher in children with metabolic syndrome, high-fat mass, high hs-CRP, larger WC, and insulin resistance significantly (for a review of P-values between two groups)." (PMID 36859176, 2023). "The PCOS women versus the controls had comparable insulin resistance and systemic inflammation (C-reactive protein 2.0 mg/L vs. 2.3 mg/L, p > 0.05), but higher free androgen index and anti-mullerian hormone levels." (PMID 37509682, 2023). "Green keywords included oxidative stress, metabolic syndrome, insulin resistance, adipose tissue, blood pressure, cholesterol, inflammation, and C-reactive protein." (PMID 37342553, 2023).
Insulin resistance (continued). "In an early demonstration of MR, used MR to estimate the effect of C-Reactive Protein on insulin resistance." (PMID 36265006, 2022). "These levels were positively correlated with BMI, levels of serum triacylglycerol, glucose, C-reactive protein and the degree of insulin resistance." (PMID 35729499, 2022). "Leptin has shown positive correlations with high C-reactive protein levels, as well as with insulin resistance, which have been shown to be related to CKD." (PMID 35619087, 2022). "Like PAI-1 and SAA, circulating levels of CRP have been studied in relation to insulin resistance and T2D, due to its role as a sensitive inflammatory marker." (PMID 35883605, 2022). "Regarding metabolic health, numerous studies have attempted to create a standardized definition, with some involving the parameters of high sensitivity C-reactive protein and high homeostasis model assessment of insulin resistance." (PMID 35805843, 2022). "We evaluated the anthropometric values, lipid profiles, high-sensitivity C-reactive protein (hs-CRP) level, Homeostasis model assessment for insulin resistance (HOMA-IR), and serum adipokines levels in 219 postmenopausal women." (PMID 35550473, 2022). "After additional adjustment for total cholesterol levels, renal function (eGFR), insulin resistance (HOMA-IR), and hs-CRP levels, the association was still statistically significant (Model 4, OR 1.19 [1.06–1.33], p = 0.003)." (PMID 36555350, 2022). "In a longitudinal study, A-FABP level was higher in morbid obese than in lean women and correlated positively with BMI, homeostasis model assessment of insulin resistance, tumor necrosis factor receptors, and C-reactive protein." (PMID 35207603, 2022). "After correcting for C-reactive protein (CRP) and homeostatic model assessment of insulin resistance (HOMA-IR), the relative abundance of Lachnospirales still had a significant negative correlation with testosterone level." (PMID 35399957, 2022). "We also demonstrate an inverse correlation of serum Mg2+ with glycaemic control (as HbA1c) and hs-CRP that seems to be dependent on insulin resistance." (PMID 35440685, 2022). "Improvement in insulin resistance has been reported to be related to chronic inflammation which can be measured by c-reactive protein, interleukin-6, or TNF-alpha or oxidative stress." (PMID 35242882, 2022). "Body composition, plasma leptin, adiponectin, chemerin, omentin-1, lipids, C-reactive protein (CRP), and the homeostasis model assessment index for insulin resistance (HOMA-IR) were assessed before and after the HIIT program." (PMID 35741374, 2022). "Insignificant differences in fasting blood glucose, insulin, homeostatic model assessment of insulin resistance, quantitative insulin sensitivity check index, hs-CRP and homocysteine levels were also observed after DRB intervention." (PMID 36045411, 2022). "The presence of a periodontal infection elevates the plasma levels of TNF-α, IL-6 and C-reactive protein (CRP) and insulin resistance markers such as HOMA-IR in periodontitis patients." (PMID 35327570, 2022). "For example, short term fat overfeeding was proven to induce insulin resistance and increased circulating CRP and MCP-1 in healthy volunteers." (PMID 35614978, 2022). "Comparison of anthropometric indices, hs-CRP, and insulin resistance index (postintervention) for study and control groups (N=48)." (PMID 35547420, 2022). "This link between adiponectin concentrations and C-reactive protein, the robust inflammatory marker, is separated from adiposity and insulin resistance in obese children and adolescents." (PMID 35890325, 2022). "The results remained statistically significant in post-hoc analysis and after further adjustment for homeostasis assessment (insulin resistance and hs-CRP)." (PMID 35651978, 2022). "This type of inflammation increases the levels of several immunomodulatory molecules, such as IL-1, IL-6, and TNF-α, inducing insulin resistance and regulating C-reactive protein (CRP)." (PMID 36618686, 2022).
Insulin resistance (continued). "In conclusion, plasma leptin, insulin resistance and CRP levels in schizophrenic patients are closely related to metabolic disorders in schizophrenia patients." (PMID 36090349, 2022). "As CRP is related with insulin resistance and hyperglycemia, higher CRP levels are correlated with the development of DKD by aggravating glycemic control in DM populations." (PMID 35784528, 2022). "Comparison of anthropometric indices, hs-CRP, and insulin resistance index (preintervention vs postintervention) in study and control groups (N=48)." (PMID 35547420, 2022). "This intervention showed that zinc supplementation reduces LDL, Total Cholesterol, C-reactive protein (CRP), markers of insulin resistance, fasting blood sugar, insulin, and Homeostatic Model Assessment for Insulin Resistance (HOMA-IR) in children." (PMID 36017230, 2022). "In accordance with published data, our results show that obese mice exhibited an increase in glycemia, insulinemia, HOMA-IR index indicating insulin resistance, triglyceridemia, cholesterolemia, leptinemia and plasma CRP levels." (PMID 35624723, 2022). "So, the ability of probiotics to reduce inflammation and hs-CRP can be a key indicator of their ability to reduce insulin resistance." (PMID 36160290, 2022). "Women with PCOS had a higher free androgen index and anti-Mullerian hormone, though insulin resistance was comparable to controls; likewise, C-reactive protein, a marker of inflammation, was comparable between cohorts." (PMID 36619572, 2022). "Our subgroup analysis showed that obese women in each group (i.e. GDM, normoglycemic and uncomplicated index pregnancy) had elevated CRP, an inflammatory marker and insulin resistance." (PMID 35817936, 2022). "With the recovery of mental illness and the improvement of metabolic indicators, the levels of leptin, insulin resistance and hs-CRP in the body decreased accordingly." (PMID 36090349, 2022). "This ratio has been found to be significantly reduced in patients with insulin resistance, metabolic syndrome, and high levels of C-reactive protein (CRP), a protein found to be increased during acute inflammation." (PMID 35806353, 2022). "At both ages, women with PCOS had significantly higher BMI, waist circumferences and serum levels of testosterone, CRP, insulin and fasting glucose and greater insulin resistance than reference women." (PMID 36074951, 2022). "Within 6–12 months, the high-fructose diet in monkeys produced central obesity, insulin resistance, inflammation (increased serum levels of C-reactive protein and monocyte chemoattractant protein-1), and dyslipidemia." (PMID 36551528, 2022). "Vitamin D controls DM by lowering the C-reactive protein (CRP) levels and reducing insulin resistance along with preventing cardiovascular abnormalities by improving endothelial function." (PMID 35004028, 2021). "The improvement in insulin resistance associated with HOMA-IR reduction was recorded in the evening type (p = 0.0107), and the glycosylated hemoglobin and CRP decreased in the morning chronotype (p = 0.0047 and p = 0.0039, respectively)." (PMID 34836342, 2021). "Adipose tissue dysfunction is a pro-inflammatory state associated with increased C-reactive protein (CRP) levels, insulin resistance, and decreased production of adiponectin." (PMID 34873143, 2021). "A recent randomized clinical trial showed that non-surgical periodontal treatment and a myo-inositol supplementation significantly reduced CRP levels and insulin resistance." (PMID 33849511, 2021). "Spearman's correlation analyses showed that there was significant positive correlation between hs-CRP levels and waist circumference, total triglycerides, total cholesterol, age, body mass index, and homeostasis model assessment of insulin resistance index." (PMID 34925916, 2021).
Insulin resistance (continued). "Virulent H. pylori strains induce insulin-regulating gastroduodenal hormones by inducing inflammatory factors IL6, CRP, and chronic inflammation, and ultimately increase insulin resistance." (PMID 34922625, 2021). "Elevated C-reactive protein (CRP) levels, which are related to insulin resistance and MetS, are independent predictors of CVD events." (PMID 33466692, 2021). "The evaluation of ferritin should always be performed in conjunction with inflammatory markers (hs-CRP), BMI, and insulin resistance, both in vegetarian and omnivorous individuals." (PMID 34578841, 2021). "Adiponectin, as it correlates inversely with TG, insulin resistance, C-reactive protein and waist circumference and positively with HDL-C, is when decreased a potential marker of the MS." (PMID 33805553, 2021). "A study found that increased serum CRP and IL-6 levels correlated with elevated insulin levels and higher insulin resistance index (HOMA-IR) scores, further suggesting that inflammatory factors are closely related to IR." (PMID 33714202, 2021). "Evidence suggests that CRP is positively correlated with insulin resistance, body weight, and fatty mass." (PMID 33917519, 2021). "As for IL-6, it increases insulin resistance but also increases the hepatic production of acute phase proteins such as C-reactive protein (CRP), fibrinogen, and haptoglobin, which are systemic markers of acute inflammation." (PMID 33668493, 2021). "The positive correlation between PCSK9 and waist circumference, fasting glucose, insulin resistance, systolic blood pressure, diastolic blood pressure and C-reactive protein (all p < 0.01) was observed in women only." (PMID 34041285, 2021). "More than 25% had enhanced HDL-c, insulin resistance, systemic inflammation (assessed as hs-CRP) and triglyceride levels, reaching normal values." (PMID 34836298, 2021). "Some studies have reported moderate-degrees of increase in the inflammation marker of CRP predicts the development of insulin resistance." (PMID 33478575, 2021). "A myriad of inflammatory cytokines including TNF-α, IL-6, and C-reactive protein (CRP), are increased in skeletal muscle under conditions of insulin resistance." (PMID 33922918, 2021). "Various studies have shown relationships among hyperinsulinemia, insulin resistance, and increased inflammatory mediators such as C-reactive protein with the development and progression of MetS." (PMID 34473070, 2021). "Lipid profile, liver function, endotoxin, C-reactive protein, glycemia and insulin resistance were analyzed." (PMID 33924229, 2021). "IL-6 and TNF-α are important inducers of acute-phase proteins such as CRP and have the capacity to impair intracellular insulin signaling, predominantly contributing to insulin resistance." (PMID 34452136, 2021). "Insulin resistance leads to increased levels of C-reactive protein in the myocardium, which can induce myocardial fibrosis and diastolic dysfunction as well as atrial dilation." (PMID 33588759, 2021). "CRP, as a marker of inflammation, and insulin resistance (HOMA-IR) correlated with 11 and 6 of the clotting proteins, respectively (p < 0.05)." (PMID 33674695, 2021). "The macrophages in fatty cells secrete proinflammatory cytokines such as CRP, and cytokines which impair insulin signaling, inducing insulin resistance." (PMID 34661762, 2021). "Triglycerides, HDL-Cholesterol, LDL-cholesterol, total cholesterol, C-reactive protein, and insulin resistance were considered as markers of metabolic syndrome." (PMID 33669862, 2021). "T2DM is associated with long-term chronic low-grade inflammation characterized by an increase in some inflammatory markers, such as TNF-α, IL-6, and CRP, contributing to insulin resistance and the pathogenesis of T2DM." (PMID 34955840, 2021). "On the other hand, increased CRP levels are positively correlated with insulin resistance and the incidence of T2DM." (PMID 34239559, 2021).
Insulin resistance (continued). "AFABP was directly correlated to interleukin-6 (r = 0.50), insulin resistance index (r = 0.26), and body mass index (r = 0.28) and inversely correlated to C-reactive protein (r = −0.27)." (PMID 34007846, 2021). "Higher neck fat accumulation was also associated with metabolic dysregulation and inflammation characterized by insulin resistance, elevated triglycerides, and CRP." (PMID 33731171, 2021). "In univariate linear regression analyses, all of these lipid species, with the exception of the LPI 20:4, are negatively associated with insulin resistance (HOMA-IR, fasting insulin) and, for the most part, also with BMI and CRP." (PMID 34684461, 2021). "Abrogation of cardiac insulin resistance is shown to mitigate inflammatory cardiac dysfunction by decreased production of pro-inflammatory adhesion molecules, C-reactive protein (CRP), and IL-6." (PMID 34234695, 2021). "CRP has been shown to play an active role in hepatic insulin resistance, at least partly through impairment in insulin signalling, independent of IL-6." (PMID 32828613, 2020). "One positive finding was that CRP levels had a positive correlation with fasting blood insulin levels in both diet groups, which is similar to the previous report regarding the chronic systemic inflammation, BMI, insulin resistance and CRP." (PMID 32824387, 2020). "More time spent in light PA has also been associated with specific health factors including reduced fasting glucose levels, less arterial stiffness, and lower body mass index (BMI), waist circumference, insulin resistance, and c-reactive protein (CRP)." (PMID 32992812, 2020). "Unexpectedly, the normal plasma CRP suggested that there was little systemic inflammation despite insulin resistance and abdominal obesity." (PMID 32881912, 2020). "UAE and CRP are considered as markers of endothelial dysfunction and inflammation of the arterial wall, and they are related to insulin resistance." (PMID 33003574, 2020). "Scores of homeostatic model assessment for insulin resistance (HOMA‐IR) and serum C‐reactive protein (CRP) were evaluated as indicators of insulin resistance and chronic inflammation, respectively." (PMID 32378734, 2020). "Another study reported that the impact of body mass index on insulin resistance, CRP, and adiponectin appears greater in Chinese as compared with other major Asian ethnic groups." (PMID 33551872, 2020). "Studies have shown that TNF-α, monocyte chemoattractant protein-1 (MCP-1), C-reactive protein (CRP), ILs and other inflammatory factors can promote skeletal muscle insulin resistance." (PMID 32082422, 2020). "IL-6 creates insulin resistance in the liver and enhances the hepatic synthesis of acute phase proteins such as CRP and fibrinogen." (PMID 32466598, 2020). "In contrast, interleukin-6 was reduced, with both sources of choline compared to baseline, while eggs also had an effect on lowering C-reactive protein, insulin, and insulin resistance compared to baseline." (PMID 33066009, 2020). "In accordance, we showed in our full cohort of 72 study participants that increased BMI was positively correlated with serum triglycerides, glucose, insulin, HbA1c and CRP levels, and with insulin resistance (HOMA)." (PMID 32023876, 2020). "Inflammatory markers such as WBC, neutrophil count, and CRP were statistically significantly higher in patients with insulin resistance (p = 0.004, 0.005, and 0.01, respectively)." (PMID 32907593, 2020). "The relationships between c-fPWV and high-risk LDL particles were unaffected by adjusting for LDL-c or CRP and were only mildly attenuated by adjusting for the homeostatic model for insulin resistance (HOMA-IR)." (PMID 32411471, 2020). "C-reactive protein is a prominent biomarker of insulin resistance and cardiovascular disease, and is regulated by the visceral adipose tissue." (PMID 33143306, 2020).